PDLIM7 (PDZ and LIM domain 7)
Description:
May function as a scaffold on which the coordinated assembly of proteins can occur. May play a role as an adapter that, via its PDZ domain, localizes LIM-binding proteins to actin filaments of both skeletal muscle and nonmuscle tissues. Involved in both of the two fundamental mechanisms of bone formation, direct bone formation (e.g. embryonic flat bones mandible and cranium), and endochondral bone formation (e.g. embryonic long bone development). Plays a role during fracture repair. Involved in BMP6 signaling pathway (By similarity).
Synonyms: ENIGMA; LMP1; LMP3
Tractability: PROTAC: ubiquitination databases record sites on it; its protein half-life has been measured.
Gene: Protein-coding gene on chromosome 5 (177,483,393 to 177,497,608, reverse strand). Ensembl gene ENSG00000196923.
Subcellular location: Cytoplasm; Cytoplasm, cytoskeleton
Subcellular location (Human Protein Atlas): Actin filaments; Focal adhesion sites
Pathways (Reactome):
Developmental Biology: RET signaling
Gene Ontology:
Molecular function: protein binding; actin binding; muscle alpha-actinin binding
Biological process: actin cytoskeleton organization; heart development; muscle structure development; receptor-mediated endocytosis
Cellular component: actin cytoskeleton; adherens junction; focal adhesion; cytosol; filamentous actin; stress fiber; Z disc; cytoplasm; cytoskeleton; ruffle
Genetic constraint (gnomAD): Loss-of-function variants: 33 observed, 48.48 expected, observed/expected ratio (o/e) 0.68, 90% interval 0.51 to 0.91. The synonymous counts are far from expectation, so gnomAD's model fits this gene poorly and the ratio says little. Missense variants: 604 observed, 598.19 expected, observed/expected ratio (o/e) 1.01, 90% interval 0.94 to 1.08. Synonymous variants: 295 observed, 243.16 expected, observed/expected ratio (o/e) 1.21, 90% interval 1.1 to 1.34.
Homologues: Orthologues: macaque PDLIM7 (99% identical), chimpanzee PDLIM7 (96% identical), guinea pig PDLIM7 (95% identical), rat Pdlim7 (95% identical), mouse Pdlim7 (94% identical), pig PDLIM7 (88% identical), tropical clawed frog pdlim7 (69% identical), zebrafish pdlim7 (56% identical), Caenorhabditis elegans alp-1 (37% identical), Drosophila melanogaster Zasp52 (32% identical). Paralogues in human: PDLIM5 (50% identical), LDB3 (47% identical), PDLIM1 (21% identical), PDLIM3 (21% identical), PDLIM4 (20% identical), PDLIM2 (16% identical), PRICKLE4 (15% identical).